HMGB3 (high mobility group box 3)
Description:
Multifunctional protein with various roles in different cellular compartments. May act in a redox sensitive manner. Associates with chromatin and binds DNA with a preference for non-canonical DNA structures such as single-stranded DNA. Can bend DNA and enhance DNA flexibility by looping thus providing a mechanism to promote activities on various gene promoters (By similarity). Proposed to be involved in the innate immune response to nucleic acids by acting as a cytoplasmic promiscuous immunogenic DNA/RNA sensor (By similarity). Negatively regulates B-cell and myeloid cell differentiation. In hematopoietic stem cells may regulate the balance between self-renewal and differentiation. Involved in negative regulation of canonical Wnt signaling (By similarity).
Synonyms: HMG-2a; HMG-4; HMG2A; HMG4; MGC90319
Tractability: PROTAC: ubiquitination databases record sites on it; its protein half-life has been measured.
Gene: Protein-coding gene on chromosome X (150,980,509 to 150,990,775, forward strand). Ensembl gene ENSG00000029993.
Subcellular location: Nucleus; Chromosome; Cytoplasm
Subcellular location (Human Protein Atlas): Nucleoplasm; Nucleoli
Gene Ontology:
Molecular function: protein binding; RNA binding; DNA binding, bending; double-stranded DNA binding; four-way junction DNA binding; DNA binding
Biological process: DNA geometric change; DNA recombination
Cellular component: nucleolus; nucleoplasm; cytoplasm; nucleus; chromosome
Homologues: Orthologues: guinea pig HMGB3 (99% identical), mouse Hmgb3 (98% identical), rat Hmgb3l1 (98% identical), dog HMGB3 (97% identical), rat Hmgb3l1 (90% identical), tropical clawed frog hmgb3 (88% identical), zebrafish hmgb3a (70% identical), zebrafish hmgb3b (66% identical), Drosophila melanogaster Dsp1 (47% identical), Caenorhabditis elegans hmg-1.2 (39% identical). Paralogues in human: HMGB1 (74% identical), HMGB2 (73% identical), HMGB1P1 (70% identical), HMGB4 (35% identical), UBTF (30% identical), SSRP1 (26% identical), TOX2 (26% identical), TOX3 (25% identical), TOX4 (25% identical), TOX (24% identical), SMARCE1 (22% identical), SP100 (22% identical), and 8 more.
Diseases named in the same sentence as HMGB3 in open-access papers:
HMGB3 is named in the same sentence as 68 diseases in open-access papers, as found by Europe PMC text mining. Sharing a sentence is not in itself a finding about the gene and the disease. The quoted sentences say what the papers report.
breast cancer (35 papers, 2013 to 2025). A primary or metastatic malignant neoplasm involving the breast. "According to bioinformatics analysis, the co-expression of HMGB3 with ER and PR is associated with poor prognosis in breast cancer." (PMID 39062899, 2024). "When the miR-101-5p-associated pathways in breast cancer were assessed using RNA-seq, a particular group of genes, HMGB3, ESRP1, GINS1, TPD52, SRPK1, VANGL1, and MAGOHB, were suggested to be associated with a poor prognosis of BC." (PMID 38132441, 2023). "Using The Cancer Genome Atlas (TCGA) database RNA sequencing and clinical data, we investigated the associations between HMGB3 expression and tumor mutations, prognosis, and immune infiltration in breast cancer." (PMID 36620553, 2022). "HMGB3 has been revealed to be targeted by miR-27b and is associated with tamoxifen resistance in breast cancer." (PMID 35332131, 2022). "Conversely, HMGB3 expression was negatively associated with the expression of estrogen receptor (ER) and progesterone receptor (PR) in breast cancer." (PMID 36620553, 2022). "Cox regression analysis identified high HMGB3 expression as an independently associated risk factor for breast carcinoma." (PMID 36620553, 2022). "HMGB3 was found to target miR-27b—the event associated with tamoxifen resistance in breast cancer." (PMID 39062899, 2024). "The frequency of somatic HMGB3 mutations in breast cancer samples was 0.3%." (PMID 36620553, 2022). "Suppression of HMGB3 expression mediated by various small RNAs leads to a decrease in the aggressiveness of prostate cancer cells, causes cell death, and inhibits the migration and invasion of breast cancer cells, colon, stomach, pancreatic duct adenocarcinoma, and hepatocellular carcinoma." (PMID 39062899, 2024). "HMGB3 has previously been shown to play crucial roles in human diseases, including breast cancer (BC), glioblastoma GBM, silica‐induced pulmonary inflammation, and myocardial infarction (MI)." (PMID 40099942, 2025). "In breast cancer, acting on HMGB3, miR-145-5p can inhibit the proliferation, invasion, and migration of cancer cells and also promote their apoptosis." (PMID 39062899, 2024). "Exosomal OIP5-AS1 has been demonstrated to promote resistance to trastuzumab in breast cancer through the miR-381-3p/HMGB3 axis." (PMID 39401197, 2024). "Inhibition of HMGB3 expression leads to decreased viability, proliferation, migration, and invasion of cells in breast cancer, cervical cancer, esophageal cancer, non-small-cell lung cancer (NSCLC), and stomach cancer." (PMID 39062899, 2024). "Histone deacetylase 3 increases the expression of HMGB3, promoting the immune escape of breast cancer cells by suppressing the microRNA-130a-3p axis." (PMID 39062899, 2024). "And immunohistochemistry confirmed higher HMGB3 protein expression in breast cancer tissues in clinical samples." (PMID 36620553, 2022). "Experimental tests also showed that breast cancer cells have higher expression of HMGB3, and knockdown of HMGB3 can promote the proliferation of breast cancer cells and increase sensitivity to chemotherapy." (PMID 36620553, 2022). "Pan-cancer investigation using the GEPIA and UALCAN databases revealed a high level of HMGB3 expression in different malignancies, including breast cancer." (PMID 36620553, 2022). "Evaluating the predictive value of HMGB3 expression in breast cancer is the goal of this investigation." (PMID 36620553, 2022). "With the use of the bc-GenExMiner v4.8 database, we examined the connection between HMGB3 and clinical and pathological signatures of breast cancer." (PMID 36620553, 2022). "The Kaplan-Meier method was applied to analyze the connection between HMGB3 expression and overall survival time in breast cancer." (PMID 36620553, 2022). "Overexpressed HMGB3 is closely related to tumor occurrence and reduced survival in cervical cancer, non-small-cell lung cancer, breast cancer, bladder cancer, hepatocellular carcinoma, colorectal cancer, gastric cancer, and leukemia." (PMID 35332131, 2022).
breast cancer (continued). "Breast cancer patients with high HMGB3 expression had poor overall survival, which was validated by an analysis of a separate cohort of breast cancer patients in our center." (PMID 36620553, 2022). "Higher levels of HMGB3 were found in breast cancer patients with positive nodal status (N+) than in those with negative nodal status (N-) (p=0.0220)." (PMID 36620553, 2022). "A pan-cancer investigation revealed elevated HMGB3 expression in a number of malignancies, including breast carcinoma." (PMID 36620553, 2022). "HMGB3 was reported to participate in cancer genesis and development, including gastric cancer and breast cancer, leukemia." (PMID 34753396, 2021). "A recent study showed that HMGB3 was up-regulated in breast cancer, and silencing HMGB3 can inhibit breast cancer cell proliferation and tumor growth." (PMID 33960364, 2021). "Intercellular transfer of OIP5-AS1 by exosomes enhanced trastuzumab resistance in breast cancer via miR-381-3p/HMGB3 axis, indicating a potential therapeutic strategy to boost the effectiveness of trastuzumab in resistant breast cancer patients." (PMID 33821219, 2021). "In breast cancer patients, one member of this family (HMGB3) was found to be overexpressed, and its expression correlated with worse prognosis." (PMID 31752366, 2019). "For example, downregulated miR-205 expression was observed in breast cancer, and it regulated proliferation and invasion of breast cancer cells by targeting HMGB3." (PMID 26515287, 2015). "Our findings suggest that modulating miR-205 and/or targeting HMGB3 are potential therapies for advanced breast cancer." (PMID 24098490, 2013). "To determine if a correlation exists between HMGB3 expression and patient survival, we analyzed published breast cancer data sets." (PMID 24098490, 2013). "We report that the expression of HMGB3, a member of the high mobility group protein superfamily, is increased in advanced breast cancer." (PMID 24098490, 2013). "To determine functions of HMGB3 overexpression in breast cancer, we conducted WST-1 proliferation and in vitro invasion assays in breast cancer cell lines." (PMID 24098490, 2013). "In conclusion, regulation of HMGB3 by miR-205 reduced both proliferation and invasion of breast cancer cells." (PMID 24098490, 2013). "Moreover, MMPs are downregulated in breast cancer cells following inhibition of high mobility group box-3 (Hmbg3), which was also identified as an IL-13 related gene in the current study." (PMID 40822305, 2025). "HMGB3 could regulate breast cancer cell autophagy and apoptosis, promoting cell migration, invasion and metastatic potential." (PMID 40173324, 2025). "It is important to note that HMGB3 is an oncogene that promotes, through various mechanisms, initiation, development, and resistance to chemotherapy in breast cancer, colorectal cancer, thyroid cancer, neuroblastoma, nasopharyngeal carcinoma, and cervical cancer." (PMID 39062899, 2024). "HMGB3 prevents mammosphere formation in breast cancer through binding to HIF1α." (PMID 39062899, 2024). "Importantly, HMGB3 is an oncogene that promotes tumor occurrence, development, and chemotherapy resistance, through a variety of mechanisms, in breast cancer, colorectal cancer, thyroid cancer, neuroblastoma, nasopharyngeal carcinoma, and cervical cancer." (PMID 37328851, 2023). "Similarly, HMGB3 is also a prototypical marker of breast cancer progression but worsens cancer progression primarily by promoting formation of breast layers of breast cancer cells." (PMID 36267313, 2022). "Additionally, we used IHC to confirm higher HMGB3 expression in breast cancer tissues than in adjacent normal breast tissues." (PMID 36620553, 2022). "The CPTAC also showed that breast cancer tissues had higher levels of HMGB3 protein expression." (PMID 36620553, 2022). "discussed the significant increase in HMGB3 in tamoxifen-resistant breast cancer." (PMID 36620553, 2022).
breast cancer (continued). "Inversely, HMGB3 silence decreased CD44+/CD24− subpopulation with stemness in breast cancer cells." (PMID 35416122, 2022). "More research on the connection between HMGB3 and breast cancer is needed." (PMID 36620553, 2022). "The prognostic significance of HMGB3 in breast cancer was examined and validated in this study." (PMID 36620553, 2022). "Breast cancer tissues had higher HMGB3 expression than normal breast tissues." (PMID 36620553, 2022). "Moreover, exosomal-OIP5-AS1 promoted trastuzumab chemoresistance via decoying miR-381-3p and increasing HMGB3 in breast cancer." (PMID 35756672, 2022). "In conclusion, this study demonstrated that exosome-mediated transfer of OIP5-AS1 partially induced trastuzumab resistance in breast cancer through miR-381-3p/HMGB3 axis, indicating a therapeutic strategy for the trastuzumab resistance in patients with breast cancer." (PMID 33821219, 2021). "As for HMGB3, several experiments revealed that it was upregulated by diverse noncoding RNAs, which in turn fomented malignant behaviors and even immune escape of breast cancer cells." (PMID 34777483, 2021). "In addition to being involved in angiogenesis and cell proliferation, HMGB3 is another target of miR-205-5p that is responsible for EMT in breast cancer." (PMID 31752366, 2019). "Similarly, other investigators have also shown that FOXQ1 played a key role in nasopharyngeal carcinoma, targeted by miR-506 and miR-124; likewise, HMGB3 in breast cancer is targeted by miR-205; and MKI67 in hepatocellular carcinoma, targeted by miR-519d." (PMID 27119506, 2016). "Indeed, the promoters of several breast cancer genes on the X chromosome, such as AR, HMGB3 and LAGE3, were hypomethylated and the mRNAs were over-expressed in MCF7 and HCC1954." (PMID 25706888, 2015). "It is possible therefore that HMGB3 and other oncogenic proteins may be reduced in advanced breast cancer via miR-205 derepression using epigenetic modifying drugs." (PMID 24098490, 2013). "A link between HMGB3 and the invasive, metastatic phenotype has been made by demonstrating that HMGB3 mRNA levels are increased in metastatic breast cancers, that knockdown of HMGB3 decreases in vitro invasiveness and patients with increased HMGB3 expression have poor survival." (PMID 24098490, 2013). "Moreover, we link the up-regulation of HMGB3 in breast cancer to miR-205, a miRNA that has been shown here and in other studies to have reduced expression in breast cancer." (PMID 24098490, 2013). "HMGB3 overexpression may serve as an indicator for poor breast cancer outcomes." (PMID 36620553, 2022). "Therefore, we suspected that HMGB3 might be a potential biomarker for detecting and treating breast carcinoma." (PMID 36620553, 2022). "Besides that, it has been demonstrated that HMGB3 silence could inhibit cell growth and progression in breast cancer." (PMID 33821219, 2021). "Thus, we considered that exosomal OIP5-AS1 may confer trastuzumab resistance in breast cancer cells via the regulation of miR-381-3p/HMGB3 axis." (PMID 33821219, 2021). "Furthermore, breast cancer patients with increased HMGB3 expression have worse survival." (PMID 24098490, 2013). "HMGB3, XRCC4, RGS3 and PFKL have been identified as potential target genes for breast cancer in many studies, providing more directions for the treatment of breast cancer patients." (PMID 39669558, 2024). "High-mobility group box 3 (HMGB3) is a critical regulator of cell proliferation and apoptosis in multiple cancers, including breast cancer, lung cancer, and prostate cancer." (PMID 35912216, 2022). "Treatment of breast cancer cells with 5-Aza/TSA derepressed miR-205 and reduced HMGB3 mRNA while knockdown of the transcriptional repressor NRSF/REST, reduced miR-205 and increased HMGB3." (PMID 24098490, 2013). "Thus small molecule treatment of breast cancer may impact HMGB3 via derepression of miR-205." (PMID 24098490, 2013).
breast cancer (continued). "HMGB3 inhibition inhibits colony formation and induces apoptosis by increasing reactive oxygen species accumulation and decreasing MMP, p-mTOR, and STAT3 levels in human breast cancer cells." (PMID 37328851, 2023). "HMGB3 has low or no expression in normal adult tissues but high expression in various kinds of tumor tissues, including esophageal cancer, lung cancer, breast cancer, gastric adenocarcinoma, bladder cancer, prostate cancer, and glioma." (PMID 35754798, 2022). "In addition, we evaluated the value of HMGB3 in predicting the progression-free survival (PFS) and OS of breast cancer patients in our center." (PMID 36620553, 2022). "Most of the studies on HMGB3 have focused on promoting the proliferation, invasion, and metastasis of non-small cell lung cancer, gastrointestinal tumors, and breast cancer; however, there are few studies in the non-tumor field." (PMID 32587254, 2020). "HMGB3, a member of the HMG-box family, is highly expressed in different types of cancers, including gastric cancer, esophageal squamous cell carcinoma, breast cancer, and urinary bladder cancer.13, -15,27 Recent studies indicate that HMGB3 is associated with tumorigenesis." (PMID 30343649, 2018). "Over the past decade, the carcinogenic effects of HMGB3 have been reported in a variety of tumors, including colorectal cancer (CRC), breast cancer (BC), cervical cancer, and non-small cell lung cancer (NSCLC)." (PMID 34988076, 2021). "However, the analysis of PFS revealed that high expression of HMGB3 was associated with poor survival in patients with the HER2-positive and ER-positive breast cancer subtypes (p<0.001), but not in those with the TNBC breast cancer subtype (p=0.134)." (PMID 36620553, 2022).
gastric cancer (15 papers, 2017 to 2025). A primary or metastatic malignant neoplasm involving the stomach. "Knockdown of HMGB3 suppresses the proliferation of cancer cells, stops their migration, and affects sensitivity to gastric cancer chemotherapy." (PMID 39062899, 2024). "In the cases of lung and gastric cancer, HMGB3 is regulated by miR-513b through the mTOR signaling pathway." (PMID 39062899, 2024). "Reducing the expression of HMGB3 leads to inhibition of invasion and migration of gastric cancer cells by suppressing the activation of MMP2 and MMP9." (PMID 39062899, 2024). "In gastric cancer cells, HMGB3 promotes cell invasion and migration by modulating MMP2 and MMP9 expression." (PMID 39684631, 2024). "HMGB3 mRNA expression in gastric cancer correlated positively with immune infiltrates in Th2 cells and T helper cells and negatively with those in mast cells and B cells." (PMID 39062899, 2024). "According to previous studies, HMGB3 can act as an oncogene that promotes tumor growth in gastric cancer, lung cancer, laryngeal squamous cell carcinoma, bladder cancer and glioblastoma." (PMID 35712661, 2022). "Collectively, our study demonstrated that MiR-18 promoted gastric cancer stemness by targeting Meis2 to suppress HMGB3 expression." (PMID 35416122, 2022). "Studies have revealed that HMGB3 can accelerate the growth of a number of tumors, including endometrial cancer, gastric carcinoma, and cervical cancer, and is a standalone indicator of poor prognosis." (PMID 36620553, 2022). "For example, upregulation of HMGB3 was identified in gastric cancer, and knockdown of HMGB3 inhibited proliferation and migration of gastric cancer cells." (PMID 32131767, 2020). "HMGB3 belongs to the high-mobility group box subfamily and has been found to be overexpressed in gastric cancer." (PMID 30343649, 2018). "In vitro, by directly affecting the expression of mitogen-activated protein kinase 1 (MAPK1), miR-633 can inhibit proliferation, invasion, and migration of gastric cancer cells; arrest the cell cycle in the G1 phase; and induce apoptosis by regulating several genes, including HMGB3." (PMID 39062899, 2024). "Furthermore, we also found that the low-expressed oncogene HMGB3 is involved in this miR-18/Meis2 axis to further promote the stemness of gastric cancer cells." (PMID 35416122, 2022). "In gastric cancer, the mechanism of HMGB3 has been investigated, whereby knockdown of HMGB3 has been speculated to be responsible for the suppression of the cell cycle and tumor growth in gastric cancer." (PMID 34408262, 2021). "Therefore, we speculate whether miR-18 promotes the stemness of GC cells by targeting Meis2 to up-regulate the expression of HMGB3 in gastric cancer." (PMID 35416122, 2022). "Previous studies showed that HMGB3 is implicated in the development of esophageal squamous cell cancer (ESCC), leukemia, gastric cancer (GC), urinary bladder cancer and non-small cell lung cancer (NSCLC)." (PMID 34753396, 2021). "In gastric cancer, MZF1 interacts with HMGB3 to regulate the expression of target genes, thereby influencing the proliferation, metastasis, and invasion of gastric cancer cells." (PMID 40655141, 2025). "High mobility group box 3 (HMGB3), a member of the high-mobility group box (HMGB) family, was reported to be over-expressed in gastric carcinoma and bladder cancer." (PMID 28678825, 2017). "High rates of expression of HMGB3, HMGN1, HMGN2, HMGN3, and HMGN4 are shown in gastric cancer." (PMID 39062899, 2024). "In gastric cancer, miR-200b overexpression stimulates proliferation, cell invasion, and EMT, thereby suppressing tumor development and increasing sensitivity to the anticancer drug cisplatin through negative regulation of HMGB3." (PMID 39062899, 2024). "HMGB3, as a gene promoter with a significantly high score, belongs to the x-linker member of the HMG family which is closely related to the poor prognosis of gastric cancer patients." (PMID 35416122, 2022).